GCC1 (GRIP and coiled-coil domain containing 1)
Description:
Probably involved in maintaining Golgi structure.
Synonyms: FLJ22035; GCC88; GCC1P; MGC20706
Tractability: Antibody: UniProt places it where antibodies can reach, with medium confidence. PROTAC: ubiquitination databases record sites on it; its protein half-life has been measured.
Gene: Protein-coding gene on chromosome 7 (127,580,628 to 127,593,611, reverse strand). Ensembl gene ENSG00000179562.
Subcellular location: Cytoplasm; Golgi apparatus membrane
Subcellular location (Human Protein Atlas): Golgi apparatus; Cytosol; Plasma membrane
Pathways (Reactome):
Vesicle-mediated transport: Retrograde transport at the Trans-Golgi-Network
Gene Ontology:
Molecular function: protein binding; small GTPase binding
Cellular component: cytosol; Golgi apparatus; Golgi trans cisterna; cytoplasm; Golgi membrane
Genetic constraint (gnomAD): Loss-of-function variants: 36 observed, 65.69 expected, observed/expected ratio (o/e) 0.55, 90% interval 0.42 to 0.72. The upper end of that interval is the gene's LOEUF score, 0.72, which puts it in group 2 of 6, group 1 being the genes least tolerant of losing a copy. Missense variants: 885 observed, 997.46 expected, observed/expected ratio (o/e) 0.89, 90% interval 0.84 to 0.94. Synonymous variants: 391 observed, 409.66 expected, observed/expected ratio (o/e) 0.95, 90% interval 0.88 to 1.04.
Homologues: Orthologues: chimpanzee GCC1 (99% identical), macaque GCC1 (98% identical), guinea pig GCC1 (94% identical), pig GCC1 (94% identical), dog GCC1 (94% identical), mouse Gcc1 (94% identical), rabbit GCC1 (94% identical), rat Gcc1 (93% identical), zebrafish gcc1 (59% identical), tropical clawed frog gcc1 (47% identical), Drosophila melanogaster GCC88 (27% identical), Caenorhabditis elegans gcc-2 (16% identical). Paralogues in human: GOLGA1 (18% identical).
Diseases named in the same sentence as GCC1 in open-access papers:
GCC1 is named in the same sentence as 7 diseases in open-access papers, as found by Europe PMC text mining. Sharing a sentence is not in itself a finding about the gene and the disease. The quoted sentences say what the papers report.
glioma (1 paper, 2021). A benign or malignant brain and spinal cord tumor that arises from glial cells (astrocytes, oligodendrocytes, ependymal cells). "Thus, we developed a prognostic prediction model for glioma patients using four mRNAs, namely, SNCG, PGD, CDK6, and GCC1." (PMID 34615480, 2021).
Obesity (1 paper, 2025). Accumulation of substantial excess body fat. "Further, we investigated in more detail selected DMRs in TSC22D1, HAS2, GCC1, NCKIPSD from SAT, all being hypermethylated in individuals with obesity and BCCIP, IL1R1 (hypermethylated in lean) and FMNL2 (hypermethylated in individuals with obesity) from OVAT." (PMID 41225618, 2025).
triple-negative breast carcinoma (1 paper, 2022). An invasive breast carcinoma which is negative for expression of estrogen receptor (ER), progesterone receptor (PR), and human epidermal growth factor receptor 2 (HER2). "To date, only one study of tiRNA-Gly-GCC-1 in another cancer was reported which demonstrated that tiRNA-Gly-GCC-1, upregulated in hypoxia-treated triple-negative breast cancer cell lines, might act as a regulatory factor involved in the hypoxia-induced chemoresistance." (PMID 36230476, 2022).
ventricular septal defect (1 paper, 2023). The presence of a defect (opening) in the septum that separates the two ventricles of the heart. "Therefore, we conclude that tRF-58:74-Gly-GCC-1 plays a crucial role in the occurrence and development of ventricular septal defect." (PMID 36826574, 2023).
tumor (1 paper, 2021). "We analyzed and visualized the relationship between four kinds of mRNAs (SNCG, PGD, CDK6, and GCC1) and tumor purity and immune cell infiltration using the TIMER tool." (PMID 34615480, 2021).
GCC1 also shares sentences with these, for which no sentence is quoted: cancer (1 paper); Urothelial Bladder Carcinoma (1).